FTO (FTO alpha-ketoglutarate dependent dioxygenase)
Diseases named in the same sentence as FTO in open-access papers (continued):
Sharing a sentence is not in itself a finding about the gene and the disease.
cardiac hypertrophy (14 papers, 2014 to 2026). "As for FTO, a well-known m6A demethylase protein, has been linked to cardiac hypertrophy and muscular contraction in cardiac remodeling." (PMID 35224032, 2022). "Third, gain- and loss-of-function studies with MeRIP-Seq showed that FTO demethylates a subset of transcripts largely associated with muscle contraction, sarcomere organization, filament sliding, and cardiac hypertrophy in primary cardiomyocytes." (PMID 34221238, 2021). "We found in FTO deficient mice signs of cardiac hypertrophy, affecting both the right and the left ventricles." (PMID 24743632, 2014). "Here, we investigated whether FTO regulates cardiac hypertrophy and the underlying mechanism of its regulatory effect." (PMID 39157458, 2024). "Surprisingly, both the protein and mRNA levels of ALKBH5 were upregulated in HFD-induced cardiac hypertrophy, while Fat mass and obesity-associated protein (FTO), the first reported m6A demethylase in eukaryotic cells, was also upregulated but not as high as ALKBH5." (PMID 39294131, 2024). "Our results highlight a key role of the m6A RNA demethylase FTO in mediating pathological cardiac hypertrophy and dysfunction following prenatal GDM exposure." (PMID 41509912, 2026). "We further analysed the FTO-mTORC1 crosstalk in the regulation of apoptosis and cardiac hypertrophy." (PMID 41327199, 2025). "To clarify the molecular mechanism through which FTO regulates cardiac hypertrophy, we conducted MeRIP sequencing in cardiomyocytes." (PMID 39157458, 2024). "In summary, our results suggest that FTO-mediated m6A demethylation plays a critical role in myocardial function and FTO knockdown in mice significantly improved myocardial hypertrophy." (PMID 39157458, 2024). "FTO, a key m6A enzyme, is involved in the pathophysiological processes leading to myocardial hypertrophy and cardiac dysfunction." (PMID 38098098, 2023). "The researchers also discovered that FTO knockdown reduced the hypertrophic response in vitro, indicating that FTO plays an essential regulatory function in cardiac hypertrophy." (PMID 35224032, 2022). "Collectively, these findings identify FTO-dependent m6A methylation as a critical epigenetic mechanism underlying GDM-induced cardiac dysfunction and suggest that targeting FTO may offer a therapeutic approach to prevent cardiac hypertrophy in offspring." (PMID 41509912, 2026). "Although the involvement of mTORC1 in compensatory hypertrophy is still debatable, in this study, we made efforts to identify the interrelation between changes in FTO dependent m6A methylations, mTORC1 and autophagy, which works as signaling events of cardiac hypertrophy and remodeling." (PMID 41327199, 2025). "Therefore, we chose FTO, a demethylase, as the crucial methylase in myocardial hypertrophy for further research." (PMID 39157458, 2024). "These researches showed that FTO might be pivotal in various cardiovascular diseases, particularly in cardiac hypertrophy, by demethylation." (PMID 39157458, 2024). "FTO overexpression could attenuate cardiac hypertrophy and remodeling and improve cardiac dysfunction and stamina compared with TAC mice." (PMID 37273867, 2023). "This implies that FTO-mTORC1-S6K1 crosstalk is necessary for both cardiac survival and cardiac hypertrophy." (PMID 41327199, 2025). "Further, it is also shown that METTL3 is indespensible for cardiac homeostasis and cardiac hypertrophy, indicating the importance of both m6A methylase (e.g. METTL3) and demethylase (FTO) in cardiac function." (PMID 41327199, 2025). "For further verification of the function of FTO in cardiac hypertrophy in vivo, AAV9 virus was injected through the tail vein to reduce FTO expression." (PMID 39157458, 2024).
cardiac hypertrophy (continued). "Finally, gene therapeutic approaches were employed to examine whether the restoration of FTO gene expression via FTO lentivirus (Lenti-FTO) could reverse GDM-induced myocardial senescence, thereby rescuing GDM-induced cardiac hypertrophy and attenuating cardiac dysfunction in offspring." (PMID 41509912, 2026). "Therefore, exaggerated cardiac sympathetic predominance in mice lacking the FTO gene could contribute directly to both ventricular hypertrophy and abnormal ventricular repolarization independent from blood pressure, conditions that might serve as a substrate for arrhythmias." (PMID 24743632, 2014).
Hepatic steatosis (14 papers, 2014 to 2025). Steatosis is a term used to denote lipid accumulation within hepatocytes. "Consistent with the findings of in vitro studies, adeno-associated viruses 8 (AAV8)-mediated FTO overexpression in the liver promoted hepatic steatosis in C57BL/6J mice." (PMID 35282837, 2022). "A case-control study in the Chinese Han population found that different variants of FTO gene like the C variant of rs1421085, T variant of rs3751812, A variant of rs8050136, and rs9939609, were associated with metabolic dysfunction-association fatty liver disease." (PMID 35923209, 2022). "Overexpression of FTO results in triglyceride accumulation in hepatocytes and AAV8-mediated FTO overexpression can promote hepatic steatosis in mice." (PMID 38545555, 2024). "Three weeks after injection, HFD-fed mice overexpressing FTO exhibited heavier LW, higher liver TG content, and more severe hepatic steatosis as compared with HFD-fed control mice." (PMID 36352530, 2023). "FTO expression was examined in a mouse model of hepatic steatosis induced by feeding mice with HFD for 16 weeks." (PMID 35282837, 2022). "The present study showed that FTO was a key player of fatty liver, which is a potential target for the treatment of NAFLD." (PMID 35282837, 2022). "Meanwhile, hepatic overexpression of FTO did not affect the body weights of mice, implying a direct role for FTO in liver steatosis." (PMID 35282837, 2022). "FTO expression was obviously elevated in the livers of mice and humans with hepatic steatosis, probably due to its decreased ubiquitination." (PMID 35282837, 2022). "To understand whether the increased FTO expression contributes to the development of hepatic steatosis, we overexpressed FTO in the liver of chow diet (CD)-fed mice by tail vein injection of FTO-expressing adenovirus (Ad-FTO)." (PMID 36352530, 2023). "Considering a decline of overall m6A methylation in liver steatosis accompanied by increased FTO expression, we speculated that the demethylase FTO might have a role in hepatic steatosis." (PMID 36352530, 2023). "Nevertheless, the physiological role of hepatic FTO during the fasting–feeding cycle and the pathophysiological role of FTO in diet-induced hepatic steatosis in mice remains unclear." (PMID 36352530, 2023). "In the current study, FTO was shown to promote hepatic steatosis in vivo." (PMID 35282837, 2022). "Altogether, FTO may promote hepatic steatosis via multiple mechanisms, including effects on de novo lipogenesis, lipid transport, and fatty acid oxidation." (PMID 35282837, 2022). "They proposed that FTO gene variations might be independent predictors of fatty liver disease in HIV-infected patients." (PMID 33817272, 2020). "Increased hepatic steatosis and fibrosis on biopsy of HIV/HCV co-infected patients were also associated with polymorphisms in the Fat Mass and Obesity-Associated Protein (FTO) gene, which may influence food consumption." (PMID 28883965, 2016). "Glucocorticoid receptor (GR)-dependent FTO transactivation and m6A demethylation on FTO mRNA promote lipid accumulation in hepatocytes; FTO knockdown dramatically attenuates dexamethasone-induced fatty liver in mice, further supporting the role of m6A on lipid synthesis." (PMID 37020540, 2023). "Inhibition of FTO by entacapone decreased the expression of SREBF1, ChREBP, and downstream lipogenic genes, ameliorating liver steatosis in HFD-fed mice." (PMID 36352530, 2023). "For example, FTO expression is increased in NAFLD, and it promotes hepatic steatosis by targeting PPARα." (PMID 37334291, 2023). "Moreover, FTO inhibited the expression of PPARα, which may mediate its role in hepatic steatosis." (PMID 35282837, 2022). "In summary, FTO is upregulated in NAFLD and suppresses the expression of PPARα in hepatocytes, leading to hepatic steatosis." (PMID 35282837, 2022).
Hepatic steatosis (continued). "In the present study, FTO was overexpressed specifically in the livers of mice by AAV8 and it promoted hepatic steatosis, consistent with the in vitro studies." (PMID 35282837, 2022). "Overall, FTO expression is increased in NAFLD, and it promotes hepatic steatosis by targeting PPARα." (PMID 35282837, 2022). "Considering the discrepancy in changes of FTO protein and mRNA in NAFLD, it was speculated that FTO may be dysregulated by the ubiquitin-proteasome system in fatty liver." (PMID 35282837, 2022). "Second, this study did not investigate the effect of deletion of FTO on liver steatosis." (PMID 35282837, 2022). "However, whether FTO takes part in hepatic steatosis in vivo has not yet been investigated." (PMID 35282837, 2022).
lung adenocarcinoma (14 papers, 2020 to 2025). A carcinoma that arises from the lung and is characterized by the presence of malignant glandular epithelial cells. "Reduced FTO expression in the liver, prostate, papillary thyroid, colorectal, and lung adenocarcinoma has been associated with poor prognosis." (PMID 36358640, 2022). "To test this, we analyzed the expression of the demethylation enzymes ALKBH5 and FTO in lung adenocarcinoma and normal tissues using the TCGA database." (PMID 39990663, 2025). "In lung adenocarcinoma, Wnt/β-catenin raised c-myc m6A levels via limiting FTO expression, thereby enhancing tumor glycolysis and tumorigenesis." (PMID 37932821, 2023). "Downregulated FTO in lung adenocarcinoma increases YTHDF1 binding to MYC mRNA, promotes MYC mRNA translation, and subsequently promotes tumour cell glycolysis, proliferation, and tumorigenesis." (PMID 36358640, 2022). "To determine the regulation of the epitranscriptome by FTO in lung adenocarcinoma, we performed m6A RNA sequencing (m6A-seq) on H322 cells with or without FTO depletion." (PMID 33966037, 2021). "To determine the expression of FTO in lung adenocarcinoma, we analyzed TCGA data and revealed that FTO expression levels were much lower in lung adenocarcinoma tissues than in their adjacent normal tissues." (PMID 33966037, 2021). "To determine the role of FTO in lung adenocarcinoma progression, we depleted FTO expression in H322 and H358 lung adenocarcinoma cells with two different shRNAs (shFTO-1 and shFTO-2)." (PMID 33966037, 2021). "Here, we demonstrate that FTO expression is downregulated and inversely correlated with poor survival of lung adenocarcinoma patients." (PMID 33966037, 2021). "Consistently, immunohistochemistry (IHC) of 83 paired tissue arrays showed that nuclear FTO expression levels were lower in the lung adenocarcinoma tissues than in their adjacent normal tissues." (PMID 33966037, 2021). "We demonstrated here that FTO expression was downregulated in lung adenocarcinoma and positively correlated with overall survival." (PMID 33966037, 2021). "Among these genes, KIAA1429, HNRNPC, YTHDC2, METTL3, WTAP, YTHDC1, and FTO were down expressed in lung adenocarcinoma, RBM15, ZC3H13, YTHDF1, YTHDF2, and ALKBH5 were up expressed." (PMID 32398949, 2020). "Of special interest, we found that Wnt signaling, which is vital in lung adenocarcinoma tumorigenesis, induced the binding of β-catenin/TCF/LEF to the TBEs of the FTO promoter region and suppressed FTO expression." (PMID 33966037, 2021). "While FTO and ALKBH5 affect the proliferation and invasion of lung adenocarcinoma cells via regulating multiple target genes and signaling pathways which are related to malignant tumors." (PMID 33193582, 2020). "Certain research suggests that Lung Squamous Cell Carcinoma (LUSC) patients with elevated FTO expression exhibit a lower survival rate, a trend not observed in Lung Adenocarcinoma (LUAD) patients." (PMID 39449798, 2024). "Our finding that FTO downregulation induced by Wnt/β-catenin signaling enhanced c-Myc expression through upregulation of m6A of MYC mRNA and subsequent YTHDF1 binding revealed a novel mechanism by which lung adenocarcinoma promotes glycolysis and growth." (PMID 33966037, 2021).
nonalcoholic fatty liver disease (14 papers, 2014 to 2025). "At the same time studies has linked FTO with non-alcoholic fatty liver disease (NAFLD)." (PMID 39192357, 2024). "Through genome-wide association studies (GWAS), we identified 6 variants previously associated with nonalcoholic fatty liver disease (NAFLD) and validated 50 shared risk variants located in ZPR1 and FTO between the Taiwanese and European populations." (PMID 39923089, 2025). "Previous study has shown that the mRNA and protein expression of FTO were upregulated in non-alcoholic fatty liver disease (NAFLD) rats, which were involved in lipid metabolism disorders." (PMID 35057432, 2022). "Accumulating evidences indicate that FTO-dependent RNA demethylation and nonalcoholic fatty liver disease are closely intertwined." (PMID 34872591, 2021). "For instance, a significant increase in FTO mRNA and protein levels has been found in the liver of non-alcoholic fatty liver disease (NAFLD) patients." (PMID 33160098, 2020). "In aggreement, FTO expression is increased in liver of a rat model of nonalcoholic fatty liver disease, and FTO overexpression increased oxydative stress and lipogenesis in L02 cells and myotubes." (PMID 24410832, 2014). "Interestingly nonalcoholic fatty liver disease (NAFLD) rat model in which the FTO overexpressed in liver showed increased oxidative stress and lipogenesis and was associated also with increased ALT levels." (PMID 28915859, 2017). "In humans, levels of FTO mRNA and protein are elevated in the liver of nonalcoholic fatty liver disease (NAFLD) patients who are also hyperglycemic and hyperinsulinemic compared to healthy control subjects." (PMID 30388740, 2018). "Interestingly, human MSC-exosomal miR-627-5p has been demonstrated to ameliorate non-alcoholic fatty liver disease via downregulating FTO expression, which indicates the inhibitory effect of FTO expression by MSC-exosomes may be mediated via exosomal miR-627-5p as well in this study." (PMID 37737187, 2023).
coronary heart disease (13 papers, 2012 to 2025). "Several studies reported that rs9939609, the most common variant of FTO, is associated with the risk of ischemic heart disease and coronary artery disease." (PMID 37238719, 2023). "As observed in Swedish men and women, FTO rs9939609 A-allele carriers have an increased risk of coronary heart disease (CHD)." (PMID 26691922, 2015). "Therefore, the FTO/circCacna1c/Hnrnpf/RIPK1 axis holds great potential as an effective target for attenuating cardiac injury caused by necroptosis in ischemic heart disease." (PMID 39533214, 2024). "The aim of the current study was to investigate the effect of a common variant of FTO gene, rs9939609 in obese and coronary heart disease (CHD) patients of Pakistan and investigate whether it has any influence on the serum biochemical parameters." (PMID 26878843, 2016). "Further studies will be needed to elucidate the full spectrum of FTO’s regulatory roles in cardiac ischemic injury and its potential as a therapeutic target for ischemic heart diseases." (PMID 39869517, 2025). "Specifically, FTO overexpression mitigated myocardial damage, reduced ROS accumulation, and promoted mitochondrial biogenesis, highlighting its potential as a therapeutic target for ischemic heart disease." (PMID 39869517, 2025). "In this case however, we know that the sample size of the study by Zimmerman is small, and there are much larger studies showing the expected effects of FTO on coronary heart disease through their effects on adiposity (rather than FTO having a direct effect on the outcome)." (PMID 22709667, 2012).
lung squamous cell carcinoma (13 papers, 2020 to 2025). "For example, FTO upregulation has been shown to drive tumor growth via MZF1 in squamous cell lung carcinoma." (PMID 40722726, 2025). "For example, high expression of the m6A demethylase FTO in lung squamous cell carcinoma indicates a poor patient prognosis." (PMID 38089085, 2022). "FTO is considered as a prognostic factor of lung squamous cell carcinoma, promoting cell proliferation and invasion, but inhibiting cell apoptosis by regulating the expression of MZF1." (PMID 35064107, 2022). "Knockdown of the FTO gene in lung squamous cell carcinoma cells was found to effectively inhibit cell proliferation and promote apoptosis, while overexpression of FTO promoted their malignant progression." (PMID 36118041, 2022). "For instance, FTO plays an oncogenic role in lung squamous cell carcinoma by decreasing m6A levels and mRNA stability of MZF1." (PMID 36105083, 2022). "For example, Alpha-Ketoglutarate Dependent Dioxygenase (FTO) was deciphered as a prognosticator for lung squamous cell carcinoma and promoted cell proliferation and invasion." (PMID 34827123, 2021). "FTO showed oncogenic functions in lung squamous cell carcinoma, enhancing MZF1 expression by decreasing the m6A levels and mRNA stability in MZF1 mRNA transcripts." (PMID 33879631, 2021). "In lung squamous cell carcinoma, the expression level of FTO is lower." (PMID 34660577, 2021). "In addition, FTO was found highly expressed in lung squamous cell carcinoma (LUSC) and knockdown FTO suppressed cancel cell viability and invasion." (PMID 32226518, 2020). "FTO can enhance the stability of MZF1 mRNA by reversing m6A modification, inducing MZF1 expression and ultimately promoting the progression of lung squamous cell carcinoma." (PMID 33029866, 2020). "In addition to FTO, METTL3 expression was also abnormal in lung squamous cell carcinoma." (PMID 34660577, 2021). "Furthermore, FTO rather than METTL3, METTL14 and ALKBH5 is considered as the main factor causing the dysfunction of m6A modification in lung squamous cell carcinoma." (PMID 33029866, 2020).
osteoarthritis (13 papers, 2014 to 2025). A noninflammatory degenerative joint disease occurring chiefly in older persons, characterized by degeneration of the articular cartilage, hypertrophy of bone at the margins and changes in the synovial membrane. "Our study aimed to assess FTO expression in different OA sequencing datasets and to meta-analyze whether FTO polymorphism was associated with the risk of osteoarthritis." (PMID 36213660, 2022). "Overexpressing FTO in osteoarthritis models improves cartilage integrity and diminishes inflammation by modulating TLR4/MyD88/NF-κB signaling and NLRP3 inflammasome activity, which are relevant in myocardial ischemia/reperfusion injury." (PMID 39980685, 2025). "FTO overexpression restores autophagy and energetic metabolism in both destabilization of the medial meniscus‐induced osteoarthritis models and FTO conditional knockout mice in meniscus cells (FTOcko)." (PMID 39804978, 2025). "FTO is a high-confidence osteoarthritis effector gene involved in skeletal development, adipogenesis, and neuronal function and development." (PMID 37433298, 2023). "Consequently, FTO overexpression suppressed synovial inflammation and alleviated osteoarthritis by inhibiting the miR-515-5p/TLR4/MyD88/NF-κB axis in an m6A-dependent manner." (PMID 39686999, 2024).